U6 (U6 spliceosomal RNA )
Gene: Small nuclear RNA gene on chromosome 12 (31,366,288 to 31,366,366, forward strand). Ensembl gene ENSG00000283256.
Gene Ontology:
Molecular function: U4 snRNA binding
Biological process: formation of quadruple SL/U4/U5/U6 snRNP; spliceosomal tri-snRNP complex assembly
Cellular component: U4/U6 x U5 tri-snRNP complex; U6 snRNP
Homologues: Orthologues: pig U6 (76% identical), dog U6 (73% identical), rabbit U6 (71% identical). Paralogues in human: RNU6-1145P (87% identical), RNU6-116P (87% identical), RNU6-15P (87% identical), RNU6-47P (87% identical), RNU6-1 (86% identical), RNU6-1060P (86% identical), RNU6-10P (86% identical), RNU6-1316P (86% identical), RNU6-132P (86% identical), RNU6-2 (86% identical), RNU6-20P (86% identical), RNU6-33P (86% identical), and 1287 more.